IL6 (interleukin 6)
Diseases named in the same sentence as IL6 in open-access papers (continued):
Sharing a sentence is not in itself a finding about the gene and the disease.
COVID-19 (continued). "For the analysis of secondary infection risk, 1,624 patients with COVID-19 including 639 treated patients and 985 controls were included, showing that anti-IL-6 signaling agents did not increase the rate of secondary infections (pooled OR = 1.21, 95% CI 0.70–2.08, p = 0.50)." (PMID 33384605, 2020). "Thus, IL-6 signaling regulated PAI-1 production in severe COVID-19 patients." (PMID 32826331, 2020). "The results of preliminary studies have shown that immune-modulatory or immune-suppressive treatments such as hydroxychloroquine, interleukin (IL)-6 and IL-1 antagonists, commonly used in rheumatology, might be considered as treatment choices for COVID-19, particularly in severe disease." (PMID 32299202, 2020). "Therefore, we suggested that IL-6 might play a key role in the cytokine storm, and interfering of IL-6 might be a potentially therapeutic for severe and critical COVID-19." (PMID 32350134, 2020). "A paper from China appearing on the preprint online platform bioRxiv reported that in patients with COVID-19, especially those admitted to the ICU, CD4+ T lymphocytes were rapidly activated in the lung to pathogenic T helper (Th) 1 cells and generated GM-CSF and IL-6." (PMID 32719685, 2020). "In addition, IL-6 levels were considered as a biomarker of disease severity and mortality and ongoing clinical trials are assessing IL-6 blockade to improve outcome in COVID-19 patients." (PMID 33384690, 2020). "Thus, in COVID-19 patients, GM-CSF potentially links the severe-pulmonary-syndrome-initiating capacity of pathogenic Th1 cells (GM-CSF+IFN-γ+) with the inflammatory signature of monocytes (CD14+CD16+ with high expression of IL-6) and their progeny." (PMID 34676125, 2020). "Interestingly, the prolonged survival of virus-target cells did not increase viral replication but rather exacerbated inflammation as demonstrated by higher levels of key inflammatory mediators such as interleukin (IL)-6, i.e. key cytokine of the “cytokine storm” characterizing COVID-19 patients." (PMID 32848765, 2020). "COVID-19 is caused by severe acute respiratory syndrome coronavirus 2 (SARS-CoV-2), which binds to the alveolar epithelial cells to subsequently activate innate and adaptive immune responses and induces the release of a large number of cytokines, including IL-6." (PMID 32765283, 2020). "While our exploratory, unadjusted analyses did not demonstrate a mortality benefit for dexamethasone or other agents, this contrasts with large randomized trials reporting benefit for corticosteroids, IL-6, and JAK inhibitors in severe COVID-19." (PMID 41496156, 2026). "For the COVID-19 group, the importance of clinical features from high to low was: PCT, IL6, RBC distribution width, etc.." (PMID 40158620, 2026). "In serum samples, soluble TLR-2 and TLR-4, IL-1β, IL-4, IL-6, Il-10, IFN-α, and TNF-α levels were significantly decreased in patients with coronavirus disease-19 (COVID-19) as compared with other viruses (p < 0.05 in each)." (PMID 41766850, 2026). "Significantly higher expression of IFN-γ (p = 0.0153), IL-6 (p < 0.0001), IL-10 (p < 0.0001), IL-17A (p = 0.0310), and TNF-α (p = 0.0034) was observed in COVID-19 patients compared to uninfected participants." (PMID 42023234, 2026). "Clinical markers such as C-reactive protein (CRP), Interleukin 6 (IL-6), and erythrocyte sedimentation rate (ESR) were found to be increased in severe COVID-19 cases." (PMID 41557029, 2026). "These interventions aim to reduce the severity of cytokine storm and prevent downstream complications, and inhibition of IL-6, IL-1, and JAK kinases has generally shown clinical benefit in COVID-19 patients." (PMID 41596316, 2026). "Future studies are required to determine how IGFBP2 inhibits cytokines—TNF-α and IL6—and chemokine—CCR5, are critical for improving COVID-19 outcomes." (PMID 40121473, 2025).
COVID-19 (continued). "Elevated IL-6 levels are commonly observed in critical illnesses such as sepsis, acute respiratory distress syndrome (ARDS), and COVID-19, leading to interest in therapeutic strategies aimed at IL-6 inhibition." (PMID 40650251, 2025). "Cytokine storm syndrome, characterized by the excessive production of pro-inflammatory cytokines such as IL-6, IL-8, and TNF-α, has been proposed as a key driver of inflammation in the pathogenesis of severe COVID-19." (PMID 40507498, 2025). "In particular, hsa_circ_0000479 is upregulated in the blood of COVID-19 patients relative to healthy controls, concomitant with increased expression of RIG-I and interleukin-6 (IL-6) and decreased levels of miR-149-5p." (PMID 40573894, 2025). "Fourth, in line with previous contributions, IL-6, LDH, and lymphocyte count can be consolidated as prognostic biomarkers of the COVID-19 clinical course." (PMID 40559541, 2025). "At very high exposure level, COVID-19-positive individuals demonstrated a continuous increase in IFN-γ, IL-2, IL-6, and IL-17A, while TNF peaked early and IL-10 showed minimal expression." (PMID 40406109, 2025). "To further analyze the predictive value of CDCA and GCDCA on the severe progression of COVID-19, we conducted ROC analysis on the predictive value of CDCA, GCDCA, neutrophils, and IL-6." (PMID 40723815, 2025). "Nearly all COVID-19 patients exhibit elevated inflammatory markers, including IL-6, hs-CRP, SAA, and PCT, exceeding normal reference ranges (IL-6: 0-7 pg/mL, hs-CRP: 0-3 mg/L, SAA: 0-6.4 mg/L, PCT: 0-0.046 ng/mL)." (PMID 40046064, 2025). "Multiple studies have confirmed a positive correlation between the severity of COVID-19 and the levels of C-reactive protein (CRP), IL-2, IL-6, IL-7, IL-8, and TNF-α cytokines." (PMID 40371107, 2025). "Among newborns with COVID-19, a strong positive correlation was observed between LUS scores and IL-6 levels." (PMID 40428193, 2025). "This includes the results of examinations defining the severity of COVID-19 and complications such as coagulation disorders or bacterial superinfections, such as CRP, PCT, leukocytes, IL-6, and D-dimers." (PMID 40943751, 2025). "Residents of EA with COVID-19 and FLS had higher production of IL-12p70, IL-6, IL-1β, IL-2, and IL-1ra compared to residents of NEA, as well as an increased production of IL-10 in COVID-19 patients." (PMID 40165959, 2025). "As a result, MSCs will increase the number of lymphocytes and regulatory DCs, boosting their antiviral properties, and resulting in lower IL-6, CRP, IL-8, and TNF levels in COVID-19 patients." (PMID 40895261, 2025). "The inflammatory processes induced by both COVID-19 and periodontitis involve various proinflammatory cytokines, including IL-1, INF-γ, IL-17, IL-8, and IL-6." (PMID 40647649, 2025). "Elevated ferritin levels were observed in both COVID-19 and non-COVID-19 patients with thrombosis, and these levels appeared to correlate with inflammatory markers, such as CRP and IL-6, and coagulation markers, including fibrinogen." (PMID 40364223, 2025). "The model was validated using experimental data from middle-aged individuals with moderate COVID-19 progression, including measurements of viral load in the upper and lower airways, serum antibodies, CD4+ and CD8+ T cells, and interleukin-6 levels." (PMID 40431602, 2025). "Patients with COVID-19, severe pneumonia, or ARDS had elevated levels of interleukin (IL)-6, IL-10, and granulocyte colony-stimulating factor (G-CSF)." (PMID 40725841, 2025). "Elevated levels of pro-inflammatory cytokines, particularly interleukin-6 (IL-6), interleukin-17 (IL-17), and tumor necrosis factor-alpha (TNF-α), are hallmarks of both CRC progression and COVID-19 severity." (PMID 41048966, 2025). "There is a substantial amount of data on cytokine storm syndrome in COVID-19 patients, particularly high circulating levels of IL-6, IL-10, IL-2R, IL-8, and TNF-α in COVID-19 patients with high mortality rates." (PMID 40508859, 2025).
COVID-19 (continued). "Periodontitis and COVID-19 share several common inflammatory pathways, such as the NLRP3/IL-1β and IL-6 signaling pathway." (PMID 40406515, 2025). "Our findings revealed that IVT mRNA with sequences identical to those used in COVID-19 vaccines triggered robust inflammation in AC16 cardiomyocytes, as evidenced by the significant upregulation of IL-6 and other inflammatory cytokines." (PMID 41200189, 2025). "During severe COVID-19-related ARDS (acute respiratory distress syndrome), specific proinflammatory cytokines such as IL-6, IL-8, and IL-10 appear at higher levels." (PMID 40497938, 2025). "The primary objective of this study was to investigate the correlation between genetic variations in IL1B, IL6, TNF, and critical outcomes of COVID-19." (PMID 40506975, 2025). "Significantly elevated levels of IL-6 have been observed in patients with severe cases of severe acute respiratory syndrome (SARS), MERS, and COVID-19 compared to milder cases and is considered as an indicator for MERS progression." (PMID 40181980, 2025). "A recent study observed significant overexpression of NEAT1 in the blood of COVID-19 patients and found that NEAT1 is significantly correlated with cytokines such as IL-6, CCL2, and TNF-α." (PMID 40285022, 2025). "For example, the rs1800629 and rs1800795 variations of proinflammatory cytokines significantly influence the clinical outcomes and systemic inflammatory profiles of COVID-19, elevating TNF-α and IL-6 levels, respectively." (PMID 40438117, 2025). "This aligns with prior work demonstrating that IL-6 overexpression - alongside TNF-α and IL-1β - correlates with severe-stage monocyte activation in COVID-19, though its independent predictive value was attenuated in comprehensive models." (PMID 41184328, 2025). "Studies have shown that circulating levels of IL-6, TNF-α, and IL-1β are significantly elevated in COVID-19 patients with severe disease." (PMID 40806851, 2025). "This should be processed especially with molecules like ivermectin, which is known for its anti-inflammatory activity and which inhibits the production of key inflammatory players involved in COVID-19, in particular NF-κB, IL1, and IL-6 in vitro and in vivo." (PMID 40869200, 2025). "In 148 patients with COVID-19 an inverse correlation was documented between ChE activity and the inflammatory markers CRP and interleukin-6." (PMID 40299464, 2025). "For example, SREBP2 activation is elevated in monocytes from COVID-19 patients, and its inhibitor, Fatostatin, suppresses the expression of pro-inflammatory cytokines such as TNF-α, IL-1β, and IL-6." (PMID 41134862, 2025). "In non-COVID-19 patients, ferritin correlated with inflammatory markers (CRP, IL-6), fibrinogen, and liver enzymes (AST, ALT, GGT)." (PMID 40364223, 2025). "In this study, the analysis of inflammatory markers (CRP, IL-6, PCT), an early warning signal of severe COVID-19 (NLR), an indicator of disease severity (eosinophils), and monocyte data in patients was performed." (PMID 40284583, 2025). "The resulting network revealed several highly connected hub proteins, including IL1B, IL6, TNF, ACE, and REN, which are central regulators of inflammatory and cardiovascular pathways known to play key roles in COVID-19 pathogenesis." (PMID 41471341, 2025). "For example, a retrospective study showed that levels of IL-6, IL-1β, and TNF-α were significantly elevated in patients with severe COVID-19, while IFN-γ levels were markedly downregulated compared to those with mild disease." (PMID 41567206, 2025). "This allows NF-κB to enter the nucleus and trigger the production of pro-inflammatory cytokines such as IL-6, IL-1β, and TNF-α, which are notably elevated in patients with severe COVID-19." (PMID 40219044, 2025). "The benefits observed in the treated groups were associated with a substantial decrease in the levels of the pro-inflammatory cytokines IL-6 and TNF-α, which are key indicators of COVID-19 severity." (PMID 40868984, 2025).
COVID-19 (continued). "In an analysis of 697 COVID-19 patients, high values of NLR, D-dimer, procalcitonin, IL-6, and CRP were predictive of mortality, with a proposed NLR cut-off of 9.9." (PMID 40869381, 2025). "Therefore, therapeutic interventions targeting the overexpression of IL-6 and glucose metabolism may serve as a promising strategy to bolster the immune response against viruses mediated by NK cells, particularly in cases where COVID-19 is comorbid with T2D." (PMID 40471558, 2025). "Whilst mRNA levels of IFN- γ, IFN-1α, MAVS, IL-6, SOCS1 and SOCS3 were similar between LTBi positive individuals in the HC and COVID-19 groups." (PMID 41468475, 2025). "The model we proposed, incorporating PCT, IL-6, monocyte percentage, lymphocyte count, and TRAIL, effectively predicts disease progression in elderly COVID-19 patients." (PMID 40426989, 2025). "All COVID-19 patient groups presented significantly higher concentrations of inflammatory cytokines, such as s-TNF-α, s-IL-1β and s-IL-6, compared to controls." (PMID 39862311, 2025). "The pro-inflammatory cytokines IL-6 and TNF were found to be increased in both analyzed compartments (p ≤ 0.05) in patients who died from COVID-19." (PMID 41210940, 2025). "Targeted inhibition of IL-6 or TNF-α has therefore been proposed to mitigate ocular surface damage and preserve tissue integrity in COVID-19 patients." (PMID 39861857, 2025). "In COVID-19 patients treated with Empagliflozin, correlations were observed between IL-1, TNF-alpha, IL-6, and blood glucose levels." (PMID 40134446, 2025). "This post hoc analysis of a trial by our study group found that IL-6, LDH, and lymphocyte count had outstanding discriminative abilities over different COVID-19 clinical milestones, which is consistent with findings from several other reviews." (PMID 40559541, 2025). "Elevated IL-6 and C-reactive protein (CRP) levels have also been found in patients with post-COVID-19 painless thyroiditis, further supporting a cytokine-driven pathophysiology." (PMID 41179091, 2025). "The IL-6 and PCT concentrations were increased in the COVID-19 ICU cohort compared with the central laboratory threshold but were not analysed in the 2.5-yr follow-up cohort." (PMID 40529720, 2025). "At low exposure levels, COVID-19-positive individuals maintained consistent production of TNF, IL-2, IL-10, and IL-6, with multiple IFN-γ peaks." (PMID 40406109, 2025). "The aim of this study was to investigate the association between cardiac (NT-proBNP and Hs-TnT) and inflammatory biomarkers (IL-6 and PCT) on the day of extubation and extubation failure in patients with COVID-19 acute respiratory distress syndrome (C-ARDS)." (PMID 39779607, 2025). "Other physiological factors that may protect against severe COVID-19 in people with cystic fibrosis (pwCF) have been discussed, including thick mucus secretion in the respiratory tract, pre-existing microbiota, elevated autophagy, and decreased interleukin 6 (IL-6) levels in the respiratory tract." (PMID 40364010, 2025). "Biomarkers such as C-reactive protein (CRP), interleukin-6 (IL-6), and lactate dehydrogenase (LDH) were identified as predictors of COVID-19 severity." (PMID 40385745, 2025). "Evidence shows that macrophage-induced inflammation in COVID-19 supports the release of proinflammatory cytokines, including interferon, TNF-α, IL-1β, IL-6, IL-10, and chemokines." (PMID 40843373, 2025). "Sepsis/septic shock patients with COVID-19 had lower C-reactive protein (CRP), procalcitonin, IL-6, basophils, and eosinophils compared to sepsis/septic shock patients of other causes." (PMID 41007672, 2025). "Cytokine storms, characterized by an excessive release of IL-6, IL-1β, and TNF-alpha, remain a central determinant of disease severity in COVID-19." (PMID 40497938, 2025).
COVID-19 (continued). "Japanese COVID-19 patients have reduced levels of inflammatory markers (e.g., CRP) and cytokines (e.g., IL-6), as well as decreased activation of the coagulation and fibrinolysis systems compared with patients from other countries." (PMID 40084335, 2025). "Supervised machine learning algorithm (RF) was used to predict the COVID-19 severity and chronicity based on immune subset profiling and a 14-plex cytokine panel (TNF-a, IL-4, IL-13, IL-2, GM-CSF, sCD40L, CCL5, CCL3, IL-6, IL-10, IFN-g, VEGF, IL-8, and CCL4." (PMID 40657638, 2025). "Pro-inflammatory cytokines, such as IL-5, IL-6, IL-9, and IL-15, were elevated in PLWH/COVID-19 compered to COVID-19-only." (PMID 41516165, 2025). "We and others demonstrated that several cytokines and chemokines including IL‐2, IL‐6, IL‐7, IL‐10, IL-15, IL-17, IP‐10, MCP‐1, TNF‐α, GCSF were related to disease severity and mortality in COVID-19." (PMID 40315230, 2025). "In the first phase of the study, participants in the acute phase of COVID-19 presented patterns of elevated inflammation in the form of high concentrations of cytokines such as TNF (TNF–α), LTA (TNF–β), IL–1β, IL–4, IL–6, IL–8, IL–13, and interferon (IFN) –α2." (PMID 40217938, 2025). "However, when tocilizumab, a humanised anti-human IL-6 receptor antibody, was pre-incubated in the COVID-19 patient’s plasma, this effect was significantly blunted, indicating that IL-6 and IL-6R may contribute to the hypercoagulability observed in clinical settings." (PMID 40497942, 2025). "Age-dependent variations in cytokine profiles have been observed: children with COVID-19 exhibit early elevation of specific cytokines (CXCL10, GM-CSF, IL-17A, and IFN-γ) but maintain lower levels of TNF and IL-6 compared to adults." (PMID 40370452, 2025). "Monoclonal antibodies against IL-6 (tocilizumab) and TNF (infliximab) have been evaluated in COVID-19 to control hyperinflammation." (PMID 40453076, 2025). "In contrast, Epstein–Barr Virus (EBV) can lead to an increase in IL-6 and CXCL10, which are known to be correlated with COVID-19 severity." (PMID 40332501, 2025). "Breastfeeding mothers with symptomatic or asymptomatic COVID-19 presented higher levels of several cytokines, such as IFN-γ, IL-4, IL-6, and TNF-α, compared to control groups." (PMID 40141241, 2025). "In patients with the PAP phase of COVID-19, an increase in proinflammatory cytokines, namely, IFN-α, TNF-α, G-CSF, IL17A, IL-6, IL1-β, and IL-13, has been confirmed in a number of studies." (PMID 40002929, 2025). "COVID-19 is known to impair all phases of wound healing through downregulation of ACE2, sustained cytokine activity (IL-6, TNF-α, IFN-γ), oxidative stress, and depletion of epidermal stem cells." (PMID 41446486, 2025). "Several biomarkers have been shown to correlate with the intensity of the inflammatory response in COVID-19: CRP, procalcitonin, IL-6, or serum ferritin." (PMID 39254783, 2025). "A drastic cytokine storm, characterized by considerably increased IL-6, IL-8, IL-10, TNF-α, and IFN levels in COVID-19 patients, leads to systemic inflammatory immune responses." (PMID 40872762, 2025). "This study elucidated a molecular mechanism linking COVID-19 mRNA vaccines to myocarditis and highlighted the ceRNA-mediated crosstalk between IVT mRNA and IL-6." (PMID 41200189, 2025). "The present study aimed to characterize IL-6/IL-10 trajectories and determine the predictive efficacy of the DBS for clinical outcomes in hospitalized COVID-19 patients, benchmarking it against WHO-CPS and IL-6 as a standalone biomarker." (PMID 41322840, 2025). "In conclusion, this study highlights the presence of endothelial dysfunction in post-COVID-19 patients, as assessed by FMD, and demonstrates statistically significant inverse correlations between FMD values, IL-6 levels, and the neutrophil-to-lymphocyte ratio." (PMID 40143236, 2025).